ITGA1 (integrin subunit alpha 1)
Diseases named in the same sentence as ITGA1 in open-access papers (continued):
Sharing a sentence is not in itself a finding about the gene and the disease.
glioblastoma (5 papers, 2021 to 2026). The most malignant astrocytic tumor (WHO grade IV). "Additionally, our scRNA-seq dataset revealed FOXP3 expression in a small proportion of glioblastoma Tregs, and expression of ITGA1, ITGAE, and CXCR6 which are associated with a Trm signature." (PMID 35464424, 2022). "Similarly, integrins CD49a (ITGA1), CD49d (ITGA4), CD51 (ITGAV), and CD11a (ITGAL) were selected for further validation based on elevated gene expression in glioblastoma-infiltrating T cells." (PMID 35464424, 2022). "Contrastively, an upregulation of ITGA1 is also observed in few numbers of cancer types such as kidney renal clear cell carcinoma (KIRC) and glioblastoma multiforme (GBM), indicating again a context-dependent function for individual integrin genes." (PMID 34715893, 2021).
liver disease (5 papers, 2012 to 2024). "Genes of inflammation and immunity (CD276, CDH6, GCKR, HNF1A, HPR, ITGA1, RORA, and STAT4) have been shown to be expressed in liver disease patients." (PMID 22530132, 2012).
lung carcinoma (5 papers, 2020 to 2025). "To determine whether Itga1 expression is required for attachment on Col1, we depleted Itga1 in mesenchymal lung cancer cells (393P_ZEB1, 344SQ, and H1299) and found that Itga1 deficiency led to reduced attachment to Col1 and cell spreading on Col1-coated wells." (PMID 34874914, 2022). "We postulated that Itga1-mediated collagen adherence is required for ZEB1-driven lung cancer progression." (PMID 34874914, 2022). "ITGA1 promotes lung cancer cell proliferation and metastasis." (PMID 39502752, 2024). "In line with this possibility, treating epithelial 393P cells or human lung cancer HCC827 cells with the DNA methyltransferase inhibitor 5-azacytidine or the histone deacetylase (HDAC) inhibitor trichostatin A (TSA) significantly upregulated Itga1 levels." (PMID 34874914, 2022). "Indeed, knockout ITGA1 could inhibit Kras-induced lung cancer in vivo, including decreased incidence of primary lung tumors and long survival by reducing cell proliferation and angiogenesis." (PMID 32071551, 2020).
colon cancer (4 papers, 2018 to 2021). "On the other hand, we also found that more abundant ITGA1 protein in colon cancer cell lines (SW480, SW620, HT29) compared to normal colonic epithelial NCM460 cells." (PMID 32071551, 2020). "In vivo and in vitro experiments proved that ITGA1 is an oncogene and may be considered a new target for colon cancer diagnosis and treatment." (PMID 33335550, 2020). "Gene α1-integrin (ITGA1) and transcription factor E2F3 have been found related to the prevention of tumor progression in colon cancer patients." (PMID 30397551, 2018).
COVID-19 (4 papers, 2021 to 2024). A disease caused by infection with severe acute respiratory syndrome coronavirus 2. "Integrin-related genes, including ITGA1, ITGB3, ITGB5, and ITGB8, have been less investigated in patients with COVID-19 myocarditis and may be potential prognostic biomarkers." (PMID 39026189, 2024). "Consistently, proteomic and metabolomics data from CMs revealed several genes (KNG1, TXNIP, ITIH4, TIMP1, SERPING1/2/3, ITGA1, ADAR, and CLIC5 etc.)and molecules (adenosine and inosine) were related with platelet activation, thus, adding antiplatelet might be a possible therapeutic for COVID-19." (PMID 35903092, 2022).
Insulin resistance (4 papers, 2018 to 2024). Increased resistance towards insulin, that is, diminished effectiveness of insulin in reducing blood glucose levels. "In mice with high-fat-induced insulin resistance, increased ITGA1 expression in hepatocytes is associated with impaired hepatic glucose metabolism, while the deletion of ITGA1 improves fatty liver conditions." (PMID 38413438, 2024). "On a high fat diet, mice with the ITGA1 gene inactivated show severe hepatic insulin resistance and decreased hepatic fat accumulation." (PMID 37662838, 2023). "In mice, knocking out Itga1 leads to severe hepatic insulin resistance and altered fatty acid metabolism when they are fed a high-fat diet." (PMID 29926116, 2018).
lung adenocarcinoma (4 papers, 2018 to 2026). A carcinoma that arises from the lung and is characterized by the presence of malignant glandular epithelial cells. "In a compendium of human lung adenocarcinoma cohorts, multiple collagen-binding receptors, including Itga1, were positively correlated with the presence of an EMT-related gene expression signature." (PMID 34874914, 2022). "Given that EMT is a key driver of acquired resistance to kinase inhibitors in lung adenocarcinoma, ITGA1 targeting strategies could address an immediate clinical need." (PMID 34874914, 2022). "Interestingly, α1 integrinI (ITGA1) mRNA and adenylyl cyclase 9 (ADCY9) mRNA competed for binding to miR-181b, and ZEB1 upregulated ITGA1 to activate a miR-181b-regulated ceRNA network that increased metastasis of lung adenocarcinomas." (PMID 33741027, 2021).
atherosclerosis (3 papers, 2022 to 2025). A disease characterized by the build-up of fatty material and calcium deposition in the arterial wall resulting in partial or complete occlusion of the arterial lumen. "The aberrant expression of Itga1 and Itgb8 could impair vascular remodeling and endothelial integrity, thereby promoting the progression of atherosclerosis." (PMID 40941321, 2025). "In atherosclerosis, ECs communicated extensively with pericyte cells and SMCs through LAMININ (LAMA5-(ITGA1+ITGB1), LAMA5-(ITGA7+ITGB1), LAMB2-(ITGA6+ITGB4), LAMB2-(ITGA6+ITGB1)) and COLLAGEN (COL4A1-(ITGA1+ITGB1), COL4A2-(ITGA1+ITGB1)) pathways." (PMID 40225569, 2025).
heart failure (3 papers, 2024). Inability of the heart to pump blood at an adequate rate to meet tissue metabolic requirements. "FLNA, ITGA6, ITGA1, and MDK may play an important role in neurons in heart failure with DCM." (PMID 38310240, 2024). "This suggests that elevated ITGA1 levels could serve as an early indicator of cardiac dysfunction in individuals with type 2 diabetes without HFpEF, despite absence of overt heart failure symptoms." (PMID 38413438, 2024).
liver fibrosis (3 papers, 2022 to 2025). "Functional assays, including gene knockdown and overexpression experiments, are required to confirm the importance of key ECM genes (e.g. CTSA and ITGA1) in liver fibrosis and their potential as therapeutic targets." (PMID 40901642, 2025).
osteoporosis (3 papers, 2015 to 2024). A condition of reduced bone mass, with decreased cortical thickness and a decrease in the number and size of the trabeculae of cancellous bone (but normal chemical composition), resulting in increased fracture incidence. "Several large GWAS have investigated the genetics of osteoporosis, revealing BMD-associated genes, including ESR1, LRP4, ITGA1, LRP5, SOST, SPP1, TNFRSF11A (RANK), TNFRSF11 (RANKL), and TNFRSF11B (OPG)." (PMID 39769358, 2024). "Candidate genetic locus, such as rs6867040 at the ITGA1, influencing both FPG and BMD has been identified, partly explaining the genetic contribution to the linking between FPG and osteoporosis." (PMID 36424968, 2022).
preeclampsia (3 papers, 2020 to 2025). Preeclampsia is a hypertensive disorder of pregnancy that is characterized by new-onset hypertension with proteinuria presenting after 20 weeks of gestation, and depending on mild or severe forms may initially present with severe headache, visual disturbances, and hyperreflexia. "EVTs fail to express ITGA1 in preeclampsia, which is associated with both poor trophoblast invasion and oxidative stress." (PMID 32745093, 2020). "ITGA1 and CDH5 play key roles in CTB differentiation and have potential disease associations (e.g., preeclampsia)." (PMID 32493340, 2020). "The increased ITGA1 expression may reflect a compensatory response aimed at promoting angiogenesis and vascular remodelling, potentially in response to sub-optimal spiral artery modification and compromised placental perfusion in late-onset preeclampsia." (PMID 41444673, 2025). "Although late-onset preeclampsia is not as strongly associated with placental vascular dysfunction as early-onset preeclampsia, genes such as CP, IGFBP7, CDH13, ROBO1, UNC5C, NRXN3, and ITGA1 suggest subtle changes in angiogenic pathways." (PMID 41444673, 2025).
Cirrhosis (2 papers, 2017 to 2019). A chronic disorder of the liver in which liver tissue becomes scarred and is partially replaced by regenerative nodules and fibrotic tissue resulting in loss of liver function. "Our gene expression microarray data show that liver MSCs obtained from the liver of patients with fibrosis and cirrhosis express medium levels of VLA-1 (CD49a; ITGA1) and low levels of VLA-4 (CD49d; ITGA4)." (PMID 31546729, 2019).
colorectal tumor (2 papers, 2016 to 2020). "A recent study from our group identified another integrin subunit upregulated in colorectal cancer and in colorectal tumour cell lines: ITGA1." (PMID 27014720, 2016). "The functional relevance of these data suggesting that MYC regulates ITGA1 expression at the transcriptional level was strengthened by the finding that MYC and ITGA1 protein expressions are found to be correlated in more than 72% of the colorectal tumour samples analyzed." (PMID 27014720, 2016).
dilated cardiomyopathy (2 papers, 2013 to 2020). Cardiomyopathy which is characterized by dilation and contractile dysfunction of the left and right ventricles. "Moreover, in dilated cardiomyopathy pathway core enrichment, integrins (Itga1, Itga10, Itga8 and Itgb6) and cellular components of troponin system (Tnni3, Tnnc1 and Tnnt2) appeared modulated, besides Cox and Myh genes." (PMID 24252798, 2013).
emphysema (2 papers, 2018 to 2024). "LILRA3, DCBLD1, and ITGA1 are at loci not previously associated with COPD or emphysema." (PMID 29566699, 2018).
hypertrophic cardiomyopathy (2 papers, 2020 to 2024). A condition in which the myocardium is hypertrophied without an obvious cause. "ITGA1(Integrin Subunit Alpha 1) has been shown to be associated with marginal zinc deficiency in heart tissue in vivo, which leads to the initiation and progression of hypertrophic cardiomyopathy, validating our predictions." (PMID 39202774, 2024).
malaria (2 papers, 2018 to 2020). Malaria is a serious and sometimes fatal disease caused by a parasite that commonly infects a certain type of mosquito which feeds on humans. "Expressions of Itga1 and Itga2 induced in the liver in response to infection with blood-stage malaria and vaccination take similar courses as those detected by microarrays." (PMID 33202767, 2020). "In particular, the qRT-PCR data show that Itga1 expression in response to malaria reveals a maximum in non-vaccinated mice on day 4 p.i., while the malaria-induced Itga2 expression is largely impaired until day 4 p.i., before it continuously increases, reaching maximum on day 11 p.i." (PMID 33202767, 2020).
pancreatic adenocarcinoma (2 papers, 2018 to 2026). "For example, cholangiocarcinoma (CHOL) overexpresses a large variety of subunits (e.g. ITGAV, ITGA1, ITGA4, ITGA5, ITGA11, ITGB1, ITGB2, ITGB6), whereas, the equally deadly pancreatic adenocarcinoma (PAAD) overexpresses a very limited set of integrins, including ITGA6 and ITGB4." (PMID 30046394, 2018).
pancreatic ductal adenocarcinoma (2 papers, 2020 to 2023). An infiltrating adenocarcinoma that arises from the epithelial cells of the pancreas. "For instance, ITGA1 was upregulated in pancreatic intraepithelial neoplasms and pancreatic ductal adenocarcinoma (PDAC) tissues, and was able to mediate PDAC cell migration." (PMID 32071551, 2020).
Stroke (2 papers, 2022 to 2024). Sudden impairment of blood flow to a part of the brain due to occlusion or rupture of an artery to the brain. "Similarly, genes involved in integrin cell surface interactions including Itga10, Itgb3, Vcam1, Itgb1, Itgae, Itgb7, Itga1, Itga5, Icam1, Itgb2, Pecam1, and Icam2 were depleted in male MMP-3 KO stroke brains." (PMID 39000490, 2024).
type 2 diabetes (2 papers, 2018 to 2024). "In our study, we investigated the potential of ITGA1 as a diagnostic marker for HFpEF in individuals with type 2 diabetes." (PMID 38413438, 2024). "Based on these findings, ITGA1 holds potential as a prognostic marker for identifying high-risk individuals with type 2 diabetes who are prone to cardiovascular complications." (PMID 38413438, 2024). "Here we observed that the type 2 diabetes-associated ITGA1 rs870992 G allele was associated with increased ITGA1 RNA expression in nerve, pancreas and smooth muscle tissue in up to 361 samples, albeit with modest p values (p < 0.0001)." (PMID 29926116, 2018). "Using a recessive genetic model, we identified two novel loci associated with type 2 diabetes in Greenlanders, namely rs870992 in ITGA1 on chromosome 5 (OR 2.79, p = 1.8 × 10−8), and rs16993330 upstream of LARGE1 on chromosome 22 (OR 3.52, p = 1.3 × 10−7)." (PMID 29926116, 2018). "Therefore, this study aimed to validate ITGA1 as a diagnostic biomarker for identifying individuals with type 2 diabetes who are at a higher risk of developing HFpEF." (PMID 38413438, 2024). "This suggests that ITGA1 could potentially serve as a valuable biomarker for assessing cardiac function in individuals with type 2 diabetes and for distinguishing those at a higher risk of developing HFpEF." (PMID 38413438, 2024). "However, there is currently no reported research on the relationship between serum levels of ITGA1 and cardiac remodelling associated with type 2 diabetes." (PMID 38413438, 2024). "Integrating ITGA1 into routine diagnostic protocols could improve the identification and management of HFpEF in individuals with type 2 diabetes." (PMID 38413438, 2024). "Thus, studies of phenotypes reflecting liver function in Greenlanders would be of great interest to elucidate the biological mechanisms underlying the association between variation in ITGA1 and type 2 diabetes." (PMID 29926116, 2018). "Besides the established TBC1D4 locus, we identified a novel genome-wide significant variant for risk of type 2 diabetes in ITGA1, and a variant near LARGE1 showing a suggestive association." (PMID 29926116, 2018). "However, the underlying pathogenic mechanism linking elevated circulating levels of ITGA1 to adverse left ventricular remodelling and functional impairment in individuals with type 2 diabetes remains unclear." (PMID 38413438, 2024). "Our study provides evidence supporting the involvement of ITGA1 in HFpEF among individuals with type 2 diabetes." (PMID 38413438, 2024). "This suggests that an elevated circulating level of ITGA1 is an independent predictor of heart dysfunction, encompassing impaired diastolic and systolic functions, in type 2 diabetes patients." (PMID 38413438, 2024). "We found that ITGA1 levels were significantly elevated in individuals with type 2 diabetes with HFpEF." (PMID 38413438, 2024). "In this study, we observed three loci, TBC1D4, ITGA1 and LARGE1, harbouring variants with large recessive effects on the risk of type 2 diabetes in Greenlanders, the latter, however, having weaker statistical support." (PMID 29926116, 2018). "A possible link between the ITGA1 locus and altered glucose regulation is supported by studies of type 2 diabetes-related traits." (PMID 29926116, 2018). "Modulating the expression or function of ITGA1, through the development of new drugs or repurposing existing medications, may help prevent or mitigate the onset of HFpEF in individuals with type 2 diabetes." (PMID 38413438, 2024). "Additionally, our longitudinal analysis highlighted a significant correlation between baseline ITGA1 levels and the progression of cardiac dysfunction in individuals with type 2 diabetes." (PMID 38413438, 2024). "Thus, our findings provide valuable insights into the molecular mechanisms by which ITGA1 influences myocardial fibrosis and contributes to the pathogenesis of HFpEF in individuals with type 2 diabetes." (PMID 38413438, 2024).
type 2 diabetes (continued). "ITGA1 serves as a biomarker for monitoring cardiac structural and functional damage, can be used to accurately diagnose the presence of HFpEF, and can be used to predict potential deterioration in cardiac structure and function as well as re-hospitalisation for individuals with type 2 diabetes." (PMID 38413438, 2024). "In contrast, in individuals with type 2 diabetes who display HFpEF, high ITGA1 levels indicate a more severe cardiac condition, encompassing both systolic and diastolic impairments, which may lead to a greater risk of adverse cardiovascular events and necessitate more intensive management." (PMID 38413438, 2024). "Our analysis revealed a significant elevation in integrin α1 (ITGA1) levels among individuals with type 2 diabetes and HFpEF when compared with individuals with type 2 diabetes without HFpEF." (PMID 38413438, 2024). "Individuals with type 2 diabetes and HFpEF showed significantly higher plasma ITGA1 levels than the individuals with type 2 diabetes without HFpEF." (PMID 38413438, 2024). "The analysis of ITGA1 expression revealed its upregulation in the participants with type 2 diabetes who had HFpEF when compared with those who did not." (PMID 38413438, 2024). "The novel variants in ITGA1 and LARGE1 had a high impact on risk of type 2 diabetes in Greenlanders, evident by the estimated effect sizes and by the higher frequency of type 2 diabetes among homozygous carriers compared with non-carriers (24.9% and 28.9% vs 10%)." (PMID 29926116, 2018).
adenoma (1 paper, 2020). A neoplasm arising from the epithelium. "Interestingly, semi-quantitative analysis of ITGA1 protein was even higher in tumor than adenoma (p<0.01)." (PMID 32071551, 2020). "CRC tumors expressed more abundant ITGA1 protein than non-tumor tissues adjacent to resected tumors, and adenoma samples." (PMID 32071551, 2020).
adenomyosis (1 paper, 2021). The growth of endometrial tissue inside the muscular wall of the uterine corpus. "The expression levels of ITGA1, ITGB1, LAMC1, and CKM are downregulated in the adenomyosis group compared with those in control group, while those proteins are successfully recovered by anti-NGF treatment." (PMID 32676925, 2021). "Western blotting confirmed that the expression levels of integrin alpha-1 (ITGA1), integrin beta-1 (ITGB1), laminin subunit gamma-1 (LAMC1), and creatine kinase M-type (CKM) were decreased in adenomyosis group, whereas those levels were elevated after anti-NGF treatment." (PMID 32676925, 2021). "In the present study, we found that integrin subunit α1 (ITGA1) and integrin subunit β1 (ITGB1) were decreased in adenomyosis group, while were elevated in Anti-NGF group, which might be beneficial for the embryo implantation." (PMID 32676925, 2021). "Furthermore, ITGB1, ITGA1, LAMC1, and CKM might participate in the recovery of adenomyosis." (PMID 32676925, 2021).
autoimmune inner ear disease (1 paper, 2021). A syndrome characterized by rapidly progressive sensorineural hearing loss (SNHL), that is often bilateral, and is potentially reversible. "A previous study has revealed that abnormal expression of ITGA1, which was an inflammatory-associated gene, may be associated with the development of autoimmune inner ear disease." (PMID 35010640, 2021).
cardiomyopathies (1 paper, 2024). "Suppressing ITGA1 expression has been shown to alleviate aggregation in the pathogenesis of cardiomyopathies, highlighting the strong association between abnormal ITGA1 expression and cardiac dysfunction." (PMID 38413438, 2024).
colon adenocarcinoma (1 paper, 2017). "Considering that α1 subunit/ITGA1 expression is correlated with MYC in more than 70% of colon adenocarcinomas, we postulated that the integrin α1β1 has a pro-tumoral contribution to CRC." (PMID 28933766, 2017).
dyslipidemia (1 paper, 2021). "Notably, several mediator CpGs reside in the proximity of well-established dyslipidemia genes: cg21922478 (ITGA1) and cg22976567 (LMNA)." (PMID 33823916, 2021).